OTOA (otoancorin)
Description:
May act as an adhesion molecule.
Synonyms: CT108; DFNB22
Tractability: Antibody: UniProt places it where antibodies can reach, with high confidence; its Gene Ontology location is reachable by antibodies, with high confidence; UniProt predicts a signal peptide or a membrane-spanning region.
Gene: Protein-coding gene on chromosome 16 (21,663,968 to 21,761,935, forward strand). Ensembl gene ENSG00000155719.
Subcellular location: Apical cell membrane; Secreted, extracellular space, extracellular matrix
Pathways (Reactome):
Metabolism of proteins: Post-translational modification: synthesis of GPI-anchored proteins
Gene Ontology:
Biological process: cell-matrix adhesion
Cellular component: cell surface; extracellular region; plasma membrane; apical plasma membrane
Genetic constraint (gnomAD): Loss-of-function variants: 70 observed, 103.96 expected, observed/expected ratio (o/e) 0.67, 90% interval 0.55 to 0.82. The upper end of that interval is the gene's LOEUF score, 0.82, which puts it in group 3 of 6, group 1 being the genes least tolerant of losing a copy. Missense variants: 891 observed, 1,012.8 expected, observed/expected ratio (o/e) 0.88, 90% interval 0.83 to 0.93. Synonymous variants: 365 observed, 408.88 expected, observed/expected ratio (o/e) 0.89, 90% interval 0.82 to 0.97.
Gene-disease validity (ClinGen):
ClinGen rates the evidence that OTOA causes each of these diseases.
nonsyndromic genetic hearing loss (autosomal recessive): Definitive.
Homologues: Orthologues: macaque OTOA (96% identical), pig OTOA (81% identical), rabbit OTOA (79% identical), guinea pig OTOA (79% identical), rat Otoa (79% identical), dog OTOA (77% identical), mouse Otoa (77% identical), tropical clawed frog otoa (48% identical). Paralogues in human: STRC (20% identical), MSLN (9% identical), MSLNL (9% identical).
Diseases named in the same sentence as OTOA in open-access papers:
OTOA is named in the same sentence as 14 diseases in open-access papers, as found by Europe PMC text mining. Sharing a sentence is not in itself a finding about the gene and the disease. The quoted sentences say what the papers report.
deafness (19 papers, 2014 to 2025). An inherited or acquired condition characterized by the complete loss of the ability to hear from one or both ears. "While the homozygous deletion in OTOA is a well-established cause of deafness, the pathogenicity of the ERCC4 variant identified in our patients is currently supported only by allele frequency data, in silico predictions, and clinical concordance." (PMID 39769235, 2024). "There were also three probands (SHJ3, SHJ16, and SNUH53-118) with only one definitely pathogenic mutant allele in one of three recessive deafness genes, OTOA, MYO15A, and MYO7A, respectively." (PMID 25373420, 2014). "Homozygous or compound heterozygous mutations in OTOA cause autosomal recessive deafness (DFNB22)." (PMID 39943967, 2025). "In addition, the OTOA gene, which encodes otoancorin and has a role in anchoring the extracellular matrix of the tectorial membrane to the edge of the spiral plate, has also been clarified as the causative gene of mild-to-moderate deafness." (PMID 34599366, 2022). "Several studies have shown that STRC and OTOA are two of the deafness genes that are more prone to CNVs." (PMID 36597107, 2023). "So far, CNVs have been reported in 29 non-syndromic HL-related genes, with STRC, OTOA, and GJB2/GJB6 being the most well-known genes with deafness-causing CNVs." (PMID 35710363, 2022). "The similarities between the clinical characteristics of HL in patients with OTOA and TECTA gene mutations reflect the mechanism of deafness caused by TM impairment." (PMID 31527525, 2019). "Usher gene mutations were found in most patients with atypical Usher syndrome, but the diagnosis was adjusted in case of double homozygosity for mutations in OTOA and NR2E3, genes implicated in isolated deafness and RP." (PMID 28944237, 2017). "The two cases also carried de novo deletions in another autosomal recessive deafness gene (OTOA)." (PMID 37013606, 2023). "Apart from the OTOA gene, known to be associated with an autosomal recessive form of deafness, the other genes involved in the deletion had not been previously associated with any medical condition." (PMID 33804237, 2021). "Two deafness-related genes (STRC and OTOA) have homologous regions in the human genome, which explains their low coverage in our WGS data." (PMID 35571039, 2022). "Segdups, defined as regions with > 95% homology, are features that are causally implicated in recurrent CNVs mediated by NAHR and were identified in seven deafness genes: TSPEAR (4 segdups), OTOA, STRC, MYO3A, ESPN, OTOGL, CACNA1D." (PMID 24963352, 2014). "In the group of individuals for which the deafness disease gene panel was not requested, no homozygous OTOA deletions were identified." (PMID 37891200, 2023).
hearing loss (7 papers, 2014 to 2025). "The patient was diagnosed with sensorineural hearing loss likely due to a combination of p.Gln589Argfs∗55 and a large inversion in OTOA." (PMID 39943967, 2025). "Here, Case 12 had just a 978-Kb fragment overlapping with the 16p11.2–p12.2 microdeletion region, involving four OMIM genes, among them OTOA (607038) which is associated with hearing impairment, so it was classified as likely pathogenic." (PMID 31391865, 2019). "The age-association parallels observations in OTOA-related hearing loss, possibly reflecting age-dependent expression patterns, while gender-specific regulation may underlie increased female susceptibility to OTOA variants." (PMID 40900730, 2025). "High-resolution genome-wide CNV analysis of 150 cases and 157 controls revealed deletions in genes known to be involved in hearing (e.g. GJB6, OTOA, and STRC, encoding connexin 30, otoancorin, and stereocilin, respectively), supporting CNV contributions to hearing loss phenotypes." (PMID 25528277, 2014).
Usher syndrome (1 paper, 2017). A syndromic diseae characterized by the association of sensorineural deafness (usually congenital) with retinitis pigmentosa and progressive vision loss. "In patient 93, the specific retinopathy due to NR2E3 mutation homozygosity could have indicated a diagnosis distinct from Usher syndrome, but congenital deafness resulting from the homozygous deletion of OTOA is indistinguishable from the hearing impairment in USH1." (PMID 28944237, 2017).
OTOA also shares sentences with these, for which no sentence is quoted: autosomal recessive deafness (2 papers); Hearing impairment (2); adenocarcinoma (1); Batten disease (1); Blindness (1); cancer (1); cleft lip (1); Intellectual disability (1); retinopathy (1); spinal muscular atrophy (1); squamous cell carcinoma (1).